TNF (tumor necrosis factor)
Diseases named in the same sentence as TNF in open-access papers (continued):
Sharing a sentence is not in itself a finding about the gene and the disease.
skin cancer (continued). "Thus, TNFα signaling through its receptors, TNFR1 and TNFR2, induces transcription of different AP-1-regulated genes that contribute to inflammation, keratinocyte migration and carcinogenesis, which makes TNFα a critical mediator of skin tumor promotion." (PMID 21297902, 2010). "Interestingly, evidence suggests that combining TNFα inhibitors with thiopurines, such as azathioprine, does not significantly increase the risk of skin cancer beyond what is observed with thiopurine monotherapy." (PMID 40427207, 2025). "Some studies have reported that patients taking TNF-alpha inhibitors have a higher risk of developing non-melanoma skin cancers, suggesting that long-term immune modulation may contribute to uncontrolled keratinocyte growth." (PMID 40141829, 2025). "Current evidence does not suggest an additional increase in the risk of skin cancers in IBD patients treated with combination therapy involving TNFα inhibitors and a thiopurine or methotrexate when compared to the cancer risks associated with monotherapy using either agent." (PMID 40427207, 2025). "The absence of LC in the skin led to a substantial reduction in TNF‐α mRNA levels and diminishing apoptosis induction in damaged KC, thereby leading to an accumulation of DNA‐damaged KC and potentially elevating the risk of developing skin cancer." (PMID 39288297, 2024). "In addition, TNF has also been associated with some other epithelial malignancies, particularly skin cancer, in mice, implying that TNF may play a similar tumor-accelerating role in CAC40." (PMID 37185280, 2023). "Therefore, TNF inhibitors are relatively safe with respect to cancer risk; however, in the era of high skin cancer prevalence, we should be aware of non-melanoma skin cancer when using TNF inhibitors." (PMID 36430392, 2022). "Like ciclosporin, adalimumab therapy might be associated with an increased risk of skin cancers, which confirms the need for further research not only on the efficacy but also the safety profile of anti-TNF therapies." (PMID 32774143, 2020). "We failed to observe a significant association between TNF-α rs1800629 and skin cancer." (PMID 28881857, 2017). "Nonetheless, transfer of B cells could not promote the skin cancers in Rag2−/− mice when the mice were deficient of TNF-α." (PMID 24991577, 2014). "However, in two studies including index skin cancers alone, the risk of new or recurrent cancers was statistically higher in the group on IMM (71.6 per 1000 p-y) compared to patients without therapy (50.8 per 1000 p-y, p = 0.035) and numerically higher than anti-TNFα (55.5 per 1000 p-y, p = ns)." (PMID 36672491, 2023). "The anticancer effects of SS were detected in various physiological processes and cancers previously for example in the skin cancer SS via suppressing the VEGFR-2 and TNF-alpha can increase lipid peroxide levels." (PMID 35725497, 2022). "Thus, similar to the tumor-promoting effect of inflammation as demonstrated by TNFα in skin carcinoma model, tumor cells may eventually escape the immune system by reducing the IL1RN level in the tumor microenvironment and develop into malignant cancer in late stages." (PMID 32244522, 2020). "It reverts chronic UVB-induced oxidative damage in mice skin tumors by modulating the expression of vascular endothelial growth factor (VEGF), inducible nitric oxide synthase (iNOS), tumor necrosis factor (TNF)-α, and interleukin (IL)-6." (PMID 29086815, 2017). "Activation of NF-κB transcription factors by TNFα promotes the upregulation of c-FLIP and enhances skin tumor cell survival, and confers their resistance to RAF inhibitor treatment." (PMID 31051015, 2016). "It is a safe agent preventing UVB-induced skin cancer via targeting inflammatory mediators (lowering COX-2, PGE2, PCNA, TNF-α, IL-1β, and IL-6 levels), cell cycle regulators (CDK inhibitor upregulation), and cell survival signals (cyclins D1, D2, E2 and CDKs2, 4, 6 inhibition)." (PMID 40943669, 2025).
skin cancer (continued). "It was also observed that FA therapy could reverse the chronic oxidative damage of UVB-induced skin tumors in mice while regulating the expression of VEGF, inducible nitric oxide synthase (iNOS), tumor necrosis factor-α (TNF-α), and IL-6." (PMID 37202657, 2023). "TNFα null mice are resistant to skin carcinogenesis induced by DMBA initiation with TPA or okadaic acid promotion, or by repeated DMBA exposure, which clearly demonstrates the critical role of TNFα in skin tumor promotion." (PMID 21297902, 2010). "Because only events with hospital admissions were ascertained as cancers according to the algorithm, skin cancers which usually do not require hospital admissions for diagnosis were most likely to be missed especially in TNF inhibitor non-users who have less needs for hospital visits." (PMID 35945635, 2022). "Zerumbone was also shown to suppress skin tumor initiation and promotion, inhibit inducible nitric oxide synthase (iNOS) and cyclooxygenase (COX)-2 expression, suppress free radical generation, and inhibit tumor necrosis factor (TNF)-α release in activated leukocytes." (PMID 23035900, 2012). "TNF-α knockout mice transferred of B cells could not enhance the skin cancer either." (PMID 24991577, 2014). "To demonstrate the importance of TNF-α in tumor promotion, we studied TNF-α gene expressions with both the liver tumor promoter nodularin and the mouse skin tumor promoter TPA - which is not a liver tumor promoter." (PMID 30341686, 2018).
alcoholic liver diseases (76 papers, 2003 to 2026). A disorder caused by damage to the liver parenchyma due to alcohol consumption. "Cytokines, namely IL-6, IL-10, and TNF-α, are strongly associated with the development of alcoholic liver diseases according to previous research." (PMID 37759693, 2023). "Despite the clear association of TNF with alcoholic liver disease, treatment with the anti-TNF antibody infliximab has been proven detrimental in patients with alcoholic steatohepatitis due to increased rates of infection and mortality." (PMID 33353156, 2020). "Alcoholic hepatitis is known to be associated with upregulation of serum cytokines and alcohol-related liver cirrhosis has been specifically associated with high TNFα levels, which have been used to predict mortality in alcoholic liver disease." (PMID 29408932, 2018). "The main reason for associating TNFα with alcoholic liver disease is that TNFα expression is significantly increased following chronic alcohol exposure in laboratory rodents." (PMID 26751491, 2016). "LPS signalling to TLR4 and its co-receptors stimulates Kupffer cells to release TNF-α, which causes scarring of liver tissue and ultimately alcoholic liver disease." (PMID 24400890, 2014). "The damage caused by TNF-α from Kupffer cells in the liver ranges from steatosis and inflammation to hepatocyte damage in alcoholic liver disease 40,41." (PMID 24400890, 2014). "It has been proposed that activation of the resident liver macrophages, Kupffer cells, has a pivotal role in the inflammation associated with alcohol liver disease (ALD) by secreting TNF-α as well as other cytokines." (PMID 24453428, 2013). "An increased expression of TNFα is implicated in the pathogenesis of alcoholic liver disease." (PMID 26751491, 2016). "Furthermore, pro-inflammatory cytokines elicited by LPS, such as TNF-α, have been positively associated with severity of disease in patients with severe alcoholic liver disease." (PMID 25978374, 2015). "KANK2 was principally participated in the Alcoholic liver disease, Protein digestion and absorption, NF-kappa B signaling pathway, TNF signaling pathway." (PMID 41299613, 2025). "An increase in TNF-alpha levels is common in diseases such as viral hepatitis, alcoholic liver disease (ALD), and non-alcoholic fatty liver disease (NAFLD)." (PMID 40225279, 2025). "Among the top 30 genes in the gene regulatory network, 7 genes are enriched in alcoholic liver disease (hsa04936), including TNF, IL6, IFNA1, CYP2E1, ALDH2, ADH1B, ADH1C." (PMID 38429802, 2024). "Proinflammatory cytokines like IL-6 and TNF-α play a significant role in the pathogenesis of alcoholic liver disease." (PMID 36230090, 2022). "Proinflammatory cytokines, particularly TNF-α, are involved in Kupffer cell activation, hepatic necrosis, endothelial damage, and tissue recruitment of neutrophils in alcoholic liver disease." (PMID 33163083, 2020). "Alcoholic liver disease stimulates the release of cytokines, such as TNF-α, interleukin-1β (IL-1β) and IL-6, which promote the production RANKL and osteoclastogeneis." (PMID 32151025, 2020). "Circulating levels of TNF and TNFR are elevated in patients with alcoholic liver disease and alcoholic steatohepatitis, while treatment with anti TNF antibodies protects against alcoholic liver injury in animal models." (PMID 33353156, 2020). "The combination of keywords used was “alcoholic hepatitis” or “infliximab” or “tumor necrosis factor inhibitor” or “TNF-alpha” and “alcoholic liver disease”." (PMID 31516791, 2019). "Gut-derived LPS recruits macrophages via TLR4 to overexpress inflammatory cytokines such as IL-6, TNF-α, which contribute to the inflammatory processes in alcoholic liver disease." (PMID 31116255, 2019). "SREBP-1c has been implicated in the pathogenesis of AFLD, which can be activated by ER stress, LPS and TNF-α, both of these are increased in alcoholic liver disease." (PMID 29670525, 2018).
alcoholic liver diseases (continued). "Elevated levels of the pro-inflammatory cytokines TNF-α, IL-1β, and IL-8 have been observed in alcoholic liver disease patients." (PMID 30052665, 2018). "Many treatments for alcoholic liver disease, such as opiate antagonists, hemorheologic agents, chelating agents, hepatotropic hormones, antioxidants, or TNFα antagonists, have been considered controversial." (PMID 29091708, 2017). "Direct inflammatory and cytotoxic effects of TNF-α in alcoholic liver disease are well characterized." (PMID 26801973, 2016). "In alcoholic liver disease, gut-derived LPS stimulate hepatic macrophages to produce TNF-α, interleukin-6 (IL-6), and interleukin-1β (IL-1β), which exacerbate liver injury." (PMID 25978374, 2015). "The ensuing expression of pro-inflammatory cytokines (e.g., tumor necrosis factor α [TNFα], interleukin [IL]-8, and IL-1β) results in cellular dysfunction that contributes to alcoholic liver disease (ALD)." (PMID 26695748, 2015). "Tumor necrosis factor α (TNFα) is a major pro-inflammatory cytokine whose levels are increased in the blood and liver of individuals with alcoholic liver disease (ALD)." (PMID 26695748, 2015). "During the development of alcoholic liver disease, hepatic production of proinflammatory cytokines including IL-6, tumor necrosis factor (TNF)-α, and TNF-like weak inducer of apoptosis (TWEAK) is significantly increased." (PMID 27547491, 2014). "NADPH oxidase (NOX), an enzyme complex responsible for generating superoxide, is activated in rat Kupffer cells in alcoholic liver disease, through induction of transcription factor NF-κβ and TNF-α production." (PMID 22081873, 2011). "TNF-α can induce apoptosis of hepatocytes, especially in alcoholic liver disease when hepatocytes are sensitized to TNF-α-induced apoptosis." (PMID 17156425, 2006). "Clinical studies have demonstrated that patients with alcoholic liver disease have increased levels of the inflammatory cytokines IL–1, IL–6, and TNF–α as well as the chemokine IL–8 and other cytokines." (PMID 15540802, 2003). "LPS-induced TNF-α plays a key role in the development of alcoholic liver disease." (PMID 36077080, 2022). "Indeed, in a study of an alcoholic liver disease model, treatment with recombinant human Cygb significantly inhibited Kupffer cell (KC) proliferation and tumor necrosis factor-alpha (TNF-α) expression, in LPS-stimulated KCs." (PMID 31920538, 2019). "Indeed, elevated SAH levels have been shown to sensitize hepatocytes to TNF-induced toxicity in alcoholic liver disease." (PMID 29534433, 2018). "Using this model we explored the preventive effect of several probiotic strains including LF41, LGG, and BC41 which have been shown to attenuate hepatic inflammation and liver injury in GalN-sensitized and alcoholic liver disease models, on the TNF-α and ALT expression." (PMID 25978374, 2015). "The results from the present study prompted us to hypothesize the preventive or therapeutic potential of NTP on alcoholic liver disease and non-alcoholic fatty liver disease in which IL-1β and TNFα play an important role in disease progression." (PMID 25470242, 2014). "IL-1β and TNFα are factors that promote alcoholic liver disease and NASH through NF-κB activation." (PMID 25470242, 2014). "Results of other animal studies also have supported the role of TNF–α in alcoholic liver disease." (PMID 15540801, 2003). "Moreover, in an animal model of alcoholic liver disease, L. plantarum could reduce serum TNF-α, IL-6, LPS, and hepatic malondialdehyde levels as compared with those in alcohol-fed rats alone." (PMID 39200311, 2024). "Moreover, patients with alcoholic liver disease had higher levels of TNF–α in their blood." (PMID 15540801, 2003). "LPINI involved in alcoholic liver disease and TNFAIP3 mainly related to Epstein-Barr virus infection, measles, necroptosis, NOD-like receptor signaling pathway and TNF signaling pathway." (PMID 36918862, 2023).
alcoholic liver diseases (continued). "We found that 11 genes such as IL-6, TLR4, TNF, and CASP3 were interactive targets between GRg1 and ALD, suggesting that GRg1 protected alcoholic liver damage through these targets." (PMID 36052161, 2022). "In alcoholic liver disease (ALD), Tarangabin regulates the expression levels of tumor necrosis factor (TNF)-α and toll-like receptor 4 (TLR4) mRNA by acting on the lipopolysaccharide-TLR (LPS-TLR) signaling pathway, thereby improving the severity of ALD." (PMID 34721046, 2021). "Inflammatory cytokines, such as TNF-α and IFN-γ, induce liver injury in the rat model of alcoholic liver disease (ALD)." (PMID 24385684, 2013). "Concentrations in the blood of both TNF–α and TNF receptors were correlated with the levels of endotoxin in the blood and with the stage of liver disease in patients with alcoholic liver disease." (PMID 15540802, 2003). "In alcoholic liver disease, mice fed ethanol via the Tsukamoto-French intragastric enteral method, NOX was found to increase ROS and activate NF-κB, which led to an increase in TNF-α in livers." (PMID 22081873, 2011). "The liver of patients with alcoholic liver disease (ALD), NASH, primary biliary cholangitis, or primary sclerosing cholangitis is infiltrated by CD14highCD16neg monocytes which secrete proinflammatory cytokines such as tumor necrosis factor (TNF)α, IL-1β, CCL1, and CCL2." (PMID 38730724, 2024).
fibrosarcoma (76 papers, 1990 to 2025). A malignant mesenchymal fibroblastic neoplasm affecting the soft tissue and bone. "For example, necroptosis initiated by TNF‐α alone or in combination with BV6 (a Smac mimetic) involved the accumulation of intracellular ROS in mouse fibrosarcoma cells, mouse fibroblasts, and FADD‐deficient acute lymphoblastic leukemia." (PMID 40703196, 2025). "TNFα causes necrotic cell death in mouse L929 fibrosarcoma cells through an increase in mitochondrial ROS generation as detected by the ROS probe dihydrorhodamine 123 and a variety of other methods." (PMID 19891782, 2009). "On the other hand, DHA effectively reduced TNF-α-caused necroptosis and autophagy by attenuating ROS production, ceramide production, lysosomal impairment, and cathepsin L activation in the L929 murine fibrosarcoma cell line." (PMID 35457223, 2022). "To assess the impact of WDR81 in other cell types, we compared cell death induction by ABT-737 and TNF-CHX in control and WDR81-deficient HT1080 cells, a human fibrosarcoma cell line." (PMID 41042063, 2025). "For example, TNF‐α produces enlarged mitochondria with clear matrix spaces and a lower number of cristae, in mouse fibrosarcoma WEHI‐164 cells." (PMID 40703196, 2025). "Considering that a comparable dose of TNF is inactive in the WEHI-fibrosarcoma model, these results suggest that the G4 moiety of the conjugate, like CNGRC, can indeed enable the targeted delivery of TNF to the tumor vasculature." (PMID 38289472, 2024). "For instance, tumor necrosis factor-alpha (TNF-α) causes ER stress, activating PERK, IRE1 α, and ATF6 in fibrosarcoma cells." (PMID 39451231, 2024). "Previous studies showed that indacaterol inhibited cell migration and invasion of fibrosarcoma cells with a reduction of TNFα – induced MMP-9 expression." (PMID 37904233, 2023). "The nanoparticles with the peptide and functionalized with TNF (iso1Au/TNF) and isoAu/TNF+IL12 show an antitumor effect in the in vivo model of fibrosarcoma by reducing the tumor volume." (PMID 37514119, 2023). "DHA also suppresses TNF-α-induced necrosis and apoptosis in L929 murine fibrosarcoma cells and human monocytic U937 cells." (PMID 35457223, 2022). "mTOR inhibitors suppress tumor necrosis factor (TNF)-induced necroptosis of fibrosarcoma cells by down-regulating mTOR and 4EBP1." (PMID 36139919, 2022). "DHA effectively reduced TNF-α-induced necroptosis and autophagy in the L929 mouse fibrosarcoma cell line." (PMID 35457223, 2022). "hTNF inhibition decreased tumor growth and MDSC accumulation in transplantable MCA 205 fibrosarcoma model, indicating a pro-tumorigenic function of TNF." (PMID 34054827, 2021). "In a carcinogen-induced fibrosarcoma model, Treg depletion increased numbers, proliferation, and activation of TNFα-producing intratumoral CD8+ T cells, which then induced the formation of intratumoral HEVs in a TNFR-dependent manner." (PMID 34484246, 2021). "WEHI-164 murine fibrosarcoma represents an established model in which anti-tumor activity and toxicity of TNF-based pharmaceuticals are commonly tested." (PMID 34576184, 2021). "The results indicated that secretion of tumor necrosis factor-alpha (TNFα) by macrophages can impair endothelial barrier as validated by a higher number and faster dynamics of TC-EC interactions in highly invasive fibrosarcoma cells." (PMID 32264958, 2020). "Addition of TNFα to synoviocytes, hepatocytes or fibrosarcoma cells has been shown to increase the expression of BiP/GRP78 and to activate the UPR27–29." (PMID 32042069, 2020). "The potency of Trx-reduced infliximab and adalimumab relative to untreated and IAA-treated controls were determined in TNF neutralization bioassays employing the TNF-sensitive mouse fibrosarcoma WEHI-164 cell line." (PMID 31727737, 2019).